CD4 (CD4 molecule)
Diseases named in the same sentence as CD4 in open-access papers (continued):
Sharing a sentence is not in itself a finding about the gene and the disease.
parasitemia (continued). "The potential importance for both CD4 and CD8 T-cells in determining resistance to blood stage parasitemia has been suggested by experimental infection of mice with P. chabaudi." (PMID 21935482, 2011). "In our study, malaria infections were shown to significantly decrease the frequency of CD4 and CD8 triple positive MFT cells expressing IFN-γ, TNF-α, and IL-2 in lung cells of BCG vaccinated mice when high levels of parasitemia were present." (PMID 22205939, 2011). "In this study, a significant increase of circulating CD4+CD25+FOXP3+cells producing the IL-17 was observed in infected donors, corroborating previous studies on other parasitic diseases." (PMID 22087344, 2011). "Certain parasitic infections (e.g., Cryptosporidium parvum, Isospora belli, and S. stercoralis) are more prevalent among HIV-infected patients particularly those with lower CD4+ cell counts." (PMID 21532747, 2011). "To study the influence of CD4+ and CD8+ T cells on the level of parasitemia, we calculated the Spearman correlation coefficient for 30 samples from patients infected with HIV/T." (PMID 21912712, 2011). "Triple-secreting T cells subpopulations occurred as a small percentage of both CD4+ and CD8+ T cells; interestingly, the two volunteers with delayed onset of parasitemia were among the three with the highest frequencies of multiply-positive CD8+ T cells." (PMID 22003411, 2011). "Therefore, the partial protection seen in this clinical trial could be interpreted as consistent with the murine study, since the delay to parasitemia in two volunteers may also have resulted from a reduction in the numbers of liver stages by vaccine-induced CD4+ and/or CD8+ T cells." (PMID 22003411, 2011). "Conversely, we also observed an increased number of circulating CD4+CD25+FoxP3+ T cells that produce IFN-γ and IL-17 in peripheral blood of P. vivax-infected donors, which also correlated with the levels of parasitemia." (PMID 20224778, 2010). "Our results show a significant increase of circulating CD4+CD25+FoxP3+GITR+ and CD4+CD25+FoxP3+CTLA-4+ lymphocytes in P. vivax-infected donors, which was further correlated with level of parasitemia observed in the same individuals." (PMID 20224778, 2010). "CD4+ and CD8+ T cells increased in number in response to parasitemias, with each population having a sustained increase following the third parasitemia." (PMID 19774084, 2009). "A robust anti-parasite immunological response was rapidly generated in rhesus macaques infected with the parasite alone, and the numbers of circulating CD4+ and CD8+ T cells increased in response to parasitemia." (PMID 19774084, 2009). "In all murine malarial parasite infections, mice depleted of or lacking CD4+ T cells cannot clear the parasites." (PMID 41171200, 2025). "Treatment of CD169DTR mice with diphtheriatoxin (DT) efficiently depleted MMMΦ and MZMΦ, resulting in reduced IFNγ production by CD4+ T cells in P. yoelii-infected mice, though parasitemia progression was not modulated." (PMID 40746561, 2025). "T lymphocytes are broadly classified into CD4+ helper T (Th) cells and CD8+ cytotoxic T lymphocytes (CTLs), with Th cells playing a pivotal role in orchestrating humoral and cellular immune responses against parasitic infections." (PMID 40365538, 2025). "Some nodes with many edges were considered as hub genes (CD3, CD4, and ITGA8), which may play important roles in the immune response to parasite infection." (PMID 39061520, 2024). "Our data supported previous findings that CD4 T cells are important for resolution of infection as CD4−/− mice did not clear the parasite and developed a persistent parasitemia." (PMID 38392861, 2024). "Na infecção ativa por HIV, a acentuada redução de células CD4 + expressa a deficiência de resposta TH1, 874 responsável pela ativação de CD4 + e de macrófagos capazes de secretar IFN-γ e destruir os parasitos, assim ocorrendo aumento de parasitemia e parasitismo tecidual." (PMID 37377258, 2023).
parasitemia (continued). "In sum, these results imply that once memory CD4+ T cells are induced, their maintenance does not require live parasite infection for more than 14 days." (PMID 37855243, 2023). "Following challenge, purified CD4+ T-cells (1 × 106 or 1 × 107) derived from vaccinated mice were essential for sustained survival of the recipient SCID mice and control of parasitemia compared with mice that received CD4+ T-cells from mice vaccinated with Tris-DDA/TDB only." (PMID 37962347, 2023). "Although P. chabaudi MSP-1 B5 CD4+ T cells prevent immunodeficient animals from dying, B5 T cells alone do not affect P. chabaudi parasitemia significantly unless they are pre-activated, and in the presence of parasite-specific B cells." (PMID 37205446, 2023). "Several recent findings have shown that CD8+ T cells are capable of secreting IL-10 with or without CD4+ T-cell help and are involved in the regulation of immune response during virus or parasite infection." (PMID 36046744, 2022). "From our association analysis, the decline in parasitemia among the HIV-1 positives on treatment was attributed to TS treatment and not increased CD4+ levels per se." (PMID 36506016, 2022). "The frequency of CD4+ICOS+FoxP3+ Tregs was significantly higher in lethal parasitic infection as compared to the non-lethal parasite." (PMID 35109868, 2022). "IL-10 production by Tr1 cells (CD4+ CD25− Foxp3− CD127−) was able to down-regulate iRBC-induced pro-inflammatory responses resulting in the increased growth of parasitemia in non-lethal P. yoelii XNL infection." (PMID 36146602, 2022). "TNF is produced by NK cells, CD4+ T cells, macrophages, monocytes, and neutrophils, and although there were higher parasitemias in mice depleted of TNF, this did not affect the survival of vaccinated mice." (PMID 34663097, 2021). "Taken together, we favor the interpretation that LAG-3 neutralization leads to improved control of parasitemia by rescuing functional effector CD4+ T cell responses, independent of parasite-specific Ab responses." (PMID 33519801, 2020). "Studies indicate that CD8+ T lymphocytes fail to restrain parasitemia and tissue parasitism in the absence of CD4+ T cells." (PMID 33329529, 2020). "Moreover, MZB, FoB, CD4+ T and CD8+ T cells reach peak numbers following the clearance of first peak of parasitemia." (PMID 31325372, 2019). "However, using the multiple linear regression model and performing a likelihood ratio test, expression levels of CTLA-4 on both CD4+ and CD8+ T cells were found to significantly predict the level of parasitemia in the symptomatic children." (PMID 31316497, 2019). "Mechanistically, we established that T. gondii-mediated activation of the inflammasome and IL-18 were critical to maintain robust CD4+ TH1 IFN-γ responses during parasite infection in the absence of TLR11." (PMID 31194844, 2019). "Infection was established in recipient mice that received CD4 T cells from the control group, as evidenced by increasing parasitemia and organ parasite content, but not in mice that received CD4 T cells from the pmif RNA immunized donors." (PMID 30006528, 2018). "Similarly, in this study, upon anti-ICOS administration, depletion of ICOS expressing CD4+ and CD8+ T cells led to lower parasitemia, longer survival, and ameliorated pathology." (PMID 29892278, 2018). "The effect of cDC1 depletion on the development of Th1 CD4 responses was not the mere consequence of altered parasite growth as blood parasitemia was comparable with and without DT treatment." (PMID 28935714, 2017). "Together, these results show that while increasing the numbers of IFN-γ+CD4+ T cells in Il18r1−/− mice is enough for restoring their resistance to infection to the WT level, both in terms of parasitemia and survival, this is not the case for Myd88−/− mice." (PMID 28895840, 2017).
parasitemia (continued). "In the present study, we demonstrated for the first time that IL-3-producing CD4+ memory T cells, including TRM cells, play an essential role in the basophil recruitment to the site of tick re-infestation and, thereby, contribute to the acquired protective immunity against tick infestation." (PMID 29085376, 2017). "PbA infection is suited to evaluate the role of DC on T‐cell polarization and pathogenicity during cerebral malaria, but this acute model is not well adapted to study the effects of CD4‐dependent antibody responses on parasitemia." (PMID 28935714, 2017). "Strikingly, infected BALB/c mice partially (0.1 mg mAb), but not completely (4 mg mAb), depleted of CD4+ T cells had significantly decreased parasitemia and dramatically enhanced survival, accompanied with ~80% reduced production of IFN-γ." (PMID 28936213, 2017). "(A and C) Survival; (B and D) mean parasitemia levels at day 9 pi of Il18r1−/− (A and B) or Myd88−/− mice (C and D), which received or not 1.3 × 106 CD4+ T cells purified from infected WT B6 mice." (PMID 28895840, 2017). "Treatment with anti-FasL mAb starting at 11 days after infection, but not anti-TNF or anti-TRAIL antibodies, protect CD8 T cells from AICD, improved cytokine production by CD4 T cells, activate CD8 T cells, upregulate Fas expression by CD8 T cells earlier than CD4 T cells, and decreased parasitemia." (PMID 28536576, 2017). "Although CD4+ Th17 cells play a role in the control of a variety of parasitic infections, the role of IL-17 produced by CD4+ Th17 cells in immunity to F. gignatica has not been clearly defined." (PMID 29216911, 2017). "Together, our findings provide new information on the roles of galectin-1 during parasitic infection and indicate an important role for this molecule in tissue-specific Th1 cell development, but not CD4+ T cell IL-10 production." (PMID 29075269, 2017). "All WT mice treated with rIg (n = 9) had detectable parasitemia following re-infection and depletion of CD4+ or CD8+ T cells (n = 4) did not increase parasite burden." (PMID 27217330, 2016). "However, T. gondii is an intracellular parasite, thus an immune response mediated by CD4+ Th1 and CD8+ cytotoxic T cells are the main components required to combat this parasitic infection." (PMID 27199938, 2016). "We measure the inducible upregulation of Csf1 in antigen-experienced CD4+ T cells from infected mice, and show that CD4+ T cell-derived MCSF is important for control of parasitemia and recovery of host health late in infection, coinciding with the kinetics of maximal myeloid expansion." (PMID 27923070, 2016). "By contrast, we found that the degree of parasitemia at time of diagnosis did not correlate with the frequency with which CD4+ T cells expressed CTLA4 or PD1." (PMID 27802341, 2016). "The mean CD4 count in the patients with parasitic infection (195.47 cells/μL) was lower, though not statistically significant, than that of the patients without parasitic infection (214.16 cells/μL)." (PMID 27795876, 2016). "In mice, splenic CD4 T cells producing both IFN-γ+ IL-10+(sometimes denoted as type I regulatory T cells, Tr1) can be detected already at two weeks after parasite infection and attain a plateau by one month, representing 2 to 5 % of the total splenic CD4 T cell pool." (PMID 26932389, 2016). "The vaccinated mice responded to challenge infection with a rapid and potent expansion of type 1 cytokines producing CD4+ and CD8+ T cells and cytotoxic T lymphocyte activity against infected target cells, resulting in a >2-3-fold control of acute parasitemia and tissue parasite burden." (PMID 25951312, 2015). "This suggests that CD4+ and CD8+ T cells have different effector mechanisms for parasite clearance, and that the protective immunity mediated by CD8+ T cells is important in controlling infection during the early phase, within the period of peak parasitemia." (PMID 25760084, 2015).
parasitemia (continued). "Rather, effective CD4+ T-cell help for B-cells, which can occur in the absence of IL-4, is required to control chronic parasitemia." (PMID 25628621, 2014). "The prevalence of parasite infection was increased with decreasing CD4+ T-cell count among HIV positive patients without ART." (PMID 23991132, 2013). "T. cruzi-infected recipient mice receiving CD4+CD25+ T cells from rSSP4-immunized donors developed significantly less severe cardiac inflammation (+) but higher heart parasite loads (▸) and higher blood parasitemia (○) compared to controls (◊)." (PMID 23509755, 2013). "Because SGE-3X treatment protected the mice from parasitic infection and induced significant production of IFN-γ by increasing the emigration of CD4+ T cells and CD8+ T cells, we further investigated the impact of IFN-γ production on resistance against L. braziliensis infection." (PMID 23656976, 2013). "Infant CD4+ T-cell responses to bacterial infections or vaccines have been extensively studied, whereas studies on CD8+ T-cell responses focused mainly on viral and intracellular parasite infections." (PMID 22550536, 2012). "The CD4+ T cell numbers per spleen and the capacity to control parasitemia (data not shown) were not affected by JES6-1 treatment." (PMID 22272258, 2012). "It is possible that the level of parasitemia and the level of CD4+/mm3 did not change because the reactivation was diagnosed in the initial phase of the disease and early therapy with benznidazole was administered." (PMID 21912712, 2011). "Parasitemia developed similarly in control groups and in CD4+- and CD8+-depleted groups (data not shown)." (PMID 21494565, 2011). "The co-infected animals also failed to generate proliferative responses to parasitemia by CD4+ and CD8+ T cells as well as B cells while also having a less robust anti-parasite and altered anti-SIV antibody response." (PMID 19774084, 2009). "Following SIV infection there was a slight B cell expansion, similar to the co-infected animals' CD4+ T cell response, following the subsequent parasitemia, but there was little or no proliferative response to the following parasitemias." (PMID 19774084, 2009). "Pressurized oxygen therapy reduced peripheral parasitemia, expression of TNF-α, IFN-γ and IL-10 mRNA levels and percentage of γδ and αβ CD4+ and CD8+ T lymphocytes sequestered in mice brains, thus resulting in a reduction of blood-brain barrier (BBB) dysfunction and hypothermia." (PMID 18769544, 2008). "DC function is impaired during parasite infection, as a result of ingestion of HZ, and although CD4+ T cells specific for a non-parasite antigen become activated following immunization, they fail to expand clonally as efficiently as in uninfected controls." (PMID 16611373, 2006). "However, unlike WT mice, CD4−/− mice were impaired in their ability to resolve parasitemia and uniformly maintained parasitemia levels above 20% for CD4−/− mice." (PMID 38392861, 2024). "The absence of CD4 T cells did not impact levels of peak parasitemia." (PMID 38392861, 2024). "Also, infection of Cd4-cre mice resulted in a parasitemia curve similar to the control Bhlhe40fl/fl mice (data not shown), indicating that the expression of cre itself did not impact the ability of the mice to control the infection." (PMID 37843306, 2023). "Our rationale was based on the facts that the presence of CD4+ T-cell epitopes could induce the immune response in the initial phase of infection, while CD8+ T-cell epitopes could help to guarantee the long-term immunity against parasite infection." (PMID 35891310, 2022). "Thus, CD4+IL-10+ and CD4−CD8−L-10+ T cells play essential roles in immunoregulation of parasitic infections, which may be one mechanism of immune evasion by C. cellulosae." (PMID 34540719, 2021). "In addition, CD4 cell deficient mice failed to completely clear parasitemia, and the transfer of CD4 depleted spleen cells to naïve mice challenged with B. microti failed to resolve parasitemia efficiently." (PMID 34414129, 2021).
parasitemia (continued). "Importantly, T cells, particularly CD4+ T cells, are critical for clearance of B. microti infection, which explains why SCID mice in our experiments experienced prolonged parasitemia after B. microti primary infection." (PMID 32411624, 2020). "Hence, the significant higher induction of both CD4+ and CD8+ T cells in our study at the post-challenge stage is directly associated with the absence of parasitemia on blood smear and PCR in Group B vaccinated calves up to day 100 post-challenge." (PMID 33187270, 2020). "However, neither AUC nor peak levels of CD8+ or CD4+ T cell frequencies post-2nd boost or across the entire vaccination period displayed a significant correlation with parasitemia upon Spz challenge." (PMID 30673723, 2019). "Whether or not the benefits of chronic parasitic infection where numbers of CD4+CD25+ T cells are increased in patients with MS is mediated in part or mainly by IL-5 requires investigation." (PMID 29163523, 2017). "We could then analyze the CD4 responses at day 14 pi, when parasitemia had reached a similar level as day 8 without CQ." (PMID 28935714, 2017). "Notably, Cd4-/- mice transferred with naïve B6 CD4 T cells or P2rx7-/- CD4 T cells at day 20 p.i. failed to control recrudescent parasitemia up to a month of infection." (PMID 28859168, 2017). "It is not yet clear whether or how the more modest effects of CD4+ T cell-specific Csf1 deletion on monocyte numbers and macrophage/monocyte activation contribute to the observed increases in parasitemia and morbidity in Csf1ΔCD4 mice." (PMID 27923070, 2016). "However, we also found that parasite-specific CD8+ T cells contributed to the control of parasitemia on re-infection in PD-1KO but not in WT mice, even when parasite-specific antibodies and CD4+ T cells were present in both groups." (PMID 27217330, 2016). "Besides, peak parasitemia and highest frequencies of CTLA4+ and PD1+CD4+ T cells might occur at later time points than time of diagnosis." (PMID 27802341, 2016). "This declining B cell population and the lack of a proliferative B cell response to parasitemia could possibly be due to inadequate CD4+ T cell help, either by central memory or newly activated parasite-specific naïve CD4+ T cells." (PMID 19774084, 2009). "Furthermore, HIV-1-specific CD4+ and CD8+ proliferation and cytokine production may be suppressed by immunoregulation in response to parasite infection, which may impair control of HIV-1 replication and may enhance cellular vulnerability to HIV-1 infection as well." (PMID 39057072, 2024). "In contrast, CD4+ T cell-depleted mice failed to control parasite growth and developed chronic parasitemia, losing >10% of initial body weight 20 days post-infection whether treated with anti-LAG-3 or control isotype Abs, and consistent with their requirement for Py parasite clearance." (PMID 33519801, 2020). "Therefore, we hypothesized in the absence of TLR11, IL-18 is required for robust CD4+ TH1-derived IFN-γ responses during parasite infection." (PMID 31194844, 2019). "In our study, the increase of PB CD4+CD25+ cells observed in mice with a fatal outcome occurred before the parasitemia peak, what could be impairing the development of effective protective immunity, whereas in surviving mice it was only observed when parasitemia almost cleared." (PMID 24465641, 2014). "cruzi-coinfected patients and the fact that HIV infection might favor parasite growth by itself, therapy might be considered in these coinfected patients on the basis of high parasitemia and low CD4+ count and decreased CD4+/CD8+ ratio, even though symptoms were absent." (PMID 21912712, 2011). "Mechanistic studies demonstrated that CD4+ T-cells (but not CD8+ T-cells), and Th1 and Th2 cytokines (interferon gamma and tumor necrosis factor, IL-10) were critical in controlling parasitemia and survival following challenge." (PMID 37962347, 2023).